SMG5 (SMG5 nonsense mediated mRNA decay factor)
Description:
Plays a role in nonsense-mediated mRNA decay. Does not have RNase activity by itself. Promotes dephosphorylation of UPF1. Together with SMG7 is thought to provide a link to the mRNA degradation machinery involving exonucleolytic pathways, and to serve as an adapter for UPF1 to protein phosphatase 2A (PP2A), thereby triggering UPF1 dephosphorylation. Necessary for TERT activity.
Synonyms: EST1B; KIAA1089; LPTS-RP1; LPTSRP1; RP11-54H19.7; SMG-5
Tractability: PROTAC: ubiquitination databases record sites on it; its protein half-life has been measured.
Gene: Protein-coding gene on chromosome 1 (156,249,223 to 156,282,844, reverse strand). Ensembl gene ENSG00000198952.
Subcellular location: Cytoplasm; Nucleus
Subcellular location (Human Protein Atlas): Cytoplasmic bodies; Plasma membrane; Primary cilium
Pathways (Reactome):
Metabolism of RNA: Nonsense Mediated Decay (NMD) enhanced by the Exon Junction Complex (EJC)
Gene Ontology:
Molecular function: histone deacetylase binding; protein binding; protein phosphatase 2A binding; telomerase RNA binding; telomeric DNA binding; ubiquitin protein ligase binding
Biological process: regulation of dephosphorylation; regulation of telomere maintenance; mRNA export from nucleus; nuclear-transcribed mRNA catabolic process, nonsense-mediated decay; regulation of telomere maintenance via telomerase
Cellular component: cytoplasm; cytoplasmic ribonucleoprotein granule; nonsense-mediated decay complex; nucleus; cytosol; telomerase holoenzyme complex
Genetic constraint (gnomAD): Loss-of-function variants: 53 observed, 126.15 expected, observed/expected ratio (o/e) 0.42, 90% interval 0.34 to 0.53. The upper end of that interval is the gene's LOEUF score, 0.53, which puts it in group 2 of 6, group 1 being the genes least tolerant of losing a copy. Missense variants: 1,153 observed, 1,326.9 expected, observed/expected ratio (o/e) 0.87, 90% interval 0.83 to 0.91. Synonymous variants: 477 observed, 505.93 expected, observed/expected ratio (o/e) 0.94, 90% interval 0.87 to 1.02.
Homologues: Orthologues: chimpanzee SMG5 (99% identical), macaque SMG5 (99% identical), pig SMG5 (97% identical), guinea pig SMG5 (96% identical), dog SMG5 (95% identical), chimpanzee SMG5 (93% identical), mouse Smg5 (93% identical), rat Smg5 (91% identical), rabbit SMG5 (88% identical), tropical clawed frog smg5 (74% identical), zebrafish smg5 (68% identical), Drosophila melanogaster Smg5 (26% identical). Paralogues in human: SMG7 (20% identical).
Diseases named in the same sentence as SMG5 in open-access papers:
SMG5 is named in the same sentence as 15 diseases in open-access papers, as found by Europe PMC text mining. Sharing a sentence is not in itself a finding about the gene and the disease. The quoted sentences say what the papers report.
hepatocellular carcinoma (3 papers, 2020 to 2023). A malignant tumor that arises from hepatocytes. "For instance, UPF3B and SMG5 are highly expressed in hepatocellular carcinoma (HCC) tissue and are associated with poor prognosis in these patients." (PMID 36979701, 2023). "The expression levels of SMG5, EZH2, ZNF239, and IGF2BP3 in different hepatocellular carcinomas were higher than those in the normal group in the Roessler Liver (34868_ at), Roessler Liver (203358_s_at), Roessler Liver (206261_at), and Roessler Liver (203819_s_at) studies." (PMID 33297932, 2020).
liver cancer (3 papers, 2020 to 2023). An epithelial or non-epithelial malignant neoplasm that arises from the liver. "Correlation analysis showed that TMEM79 and SMG5 played a role in promoting liver cancer progression (p = 0.001, R = 0.202)." (PMID 37936239, 2023). "We also constructed a co-expression network of SMG5 and correlated PCGs in order to discover its potential downstream target genes and to explore the possible regulation of RBPs involved in the development of liver cancer." (PMID 33228611, 2020). "We analyzed the expression of SMG5, EZH2, FBLL1, ZNF239, and IGF2BP3 in liver cancer using the Oncomine database." (PMID 33297932, 2020).
prostate carcinoma (3 papers, 2013 to 2023). A carcinoma that arises from epithelial cells of the prostate gland. "TMEM79 and SMG5 complexes may be prognostic markers for prostate cancer." (PMID 37936239, 2023). "For ETS fusion-negative prostate cancers subtypes, novel gene fusions have also been identified, including SLC45A3:BRAF, ESRP1:RAF1, SLC45A3:BRAF, ESRP1:RAF1, C15orf21:Myc, EPB41:BRAF, and TMEM79:SMG5." (PMID 23957008, 2013).
autism (1 paper, 2024). Persistent deficits in social interaction and communication and interaction as well as a markedly restricted repertoire of activity and interest as well as repetitive patterns of behavior. "In fact, changes in mRNA levels of the NMD-members SMG5 and UPF3B have been associated with intellectual syndromic and non-syndromic intellectual disability, autism, childhood onset schizophrenia and ADHD." (PMID 38637827, 2024).
gastric cancer (1 paper, 2023). A primary or metastatic malignant neoplasm involving the stomach. "SMG5 may be associated with a poorer prognosis in gastric cancer." (PMID 37936239, 2023). "SMG5 can be used to predict the prognosis of HCC in the current study and may be associated with sex- and race-specific prognostic variability in gastric cancer." (PMID 37936239, 2023).
lung adenocarcinoma (1 paper, 2022). A carcinoma that arises from the lung and is characterized by the presence of malignant glandular epithelial cells. "In this study, we continue to focus on the germline mutation of genes in lung adenocarcinoma and we have identified seven different variants (SMG5, RAB3GAF2, EI24, XDH, PTPRA, ATR, GSTZ1) in three sibling patients suffering from lung cancer." (PMID 35712480, 2022).
myeloid sarcoma (1 paper, 2025). A tumor mass composed of myeloblasts or immature myeloid cells. "The PDX 49 represents a unique case of myeloid sarcoma within this cohort, and retained STR, morphology and fusions (CBL – USP2, SMG5–CTSS, and KPNA1–CBFA2T2) identical to those of the original tumor." (PMID 40801203, 2025).
tumor (6 papers, 2014 to 2025). "This article focuses on not only the prognostic role of TMEM79 and its biological significance, including immuno-infiltration, tumor mutations and drug sensitivity, but also the interaction with SMG5 in HCC." (PMID 37936239, 2023). "SMG5 exhibited significant associations with tumor number (P = 0.01), T (P = 0.019), M (P = 0.002), and TNM stage (P = 0.001)." (PMID 37936239, 2023). "Patients with high TMEM79 and SMG5 expression had higher tumor stage and were more likely to metastasize to distant sites." (PMID 37936239, 2023). "SMG5 has extensive effects on the proliferation, survival, and tumor growth of HCC cells." (PMID 37936239, 2023). "The molecules that were differentially expressed in tumor and normal tissues by R software analysis were TMEM79, SMG5, NAA35, SLC45A3, FLG, TMEM254." (PMID 37936239, 2023). "GO and KEGG analyses of these SMG5-related PCGs revealed them to be primarily enriched in the mTOR, AMPK, VEGF, and hepatitis B signaling pathways, indicating that they are closely related to tumor development." (PMID 33228611, 2020).
infection (1 paper, 2023). The state of being infected such as from the introduction of a foreign agent such as serum, vaccine, antigenic substance or organism. "We found a significant decrease of DExH-Box Helicase 34 (DHX34), suppressor with morphogenetic effect on genitalia 5 (SMG5), and SMG7 expression at 6 h post-infection, followed by a significant increase of these genes and also UPF1 and UPF2 at 9 h post-infection." (PMID 36768954, 2023). "Similarly, SMG5 and SMG7 were significantly decreased at 6 compared to that at 3 h after infection, while at 9 h post-infection, they were significantly higher than at 1 and 6 h." (PMID 36768954, 2023).
SMG5 also shares sentences with these, for which no sentence is quoted: cancer (1 paper); childhood onset schizophrenia (1); Intellectual disability (1); lung carcinoma (1); Obesity (1); viral infections (1).